LINC00882 (long independently transcribed non-coding RNA 882)
Gene: Long non-coding RNA gene on chromosome 3 (106,630,469 to 107,240,671, reverse strand). Ensembl gene ENSG00000242759.
Diseases named in the same sentence as LINC00882 in open-access papers:
LINC00882 is named in the same sentence as 2 diseases in open-access papers, as found by Europe PMC text mining. Sharing a sentence is not in itself a finding about the gene and the disease. The quoted sentences say what the papers report.
hepatocellular carcinoma (1 paper, 2022). A malignant tumor that arises from hepatocytes. "LINC00882 is upregulated by activating transcription factor (ATF) in hepatocellular carcinoma and promotes tumor progression by abolishing miR-214-3p-mediated degradation of centromere protein M mRNA." (PMID 35030969, 2022).
LINC00882 also shares sentences with these, for which no sentence is quoted: tumor (1 paper).